CSF2 (colony stimulating factor 2)
Diseases named in the same sentence as CSF2 in open-access papers (continued):
Sharing a sentence is not in itself a finding about the gene and the disease.
tumor (continued). "Moreover, these tumors are also highly enriched in factors that recruit or support suppressive monocytic MDSC or tumor associated macrophage populations (CCR2, CSF1R, and GM-CSF/CSF2)." (PMID 30388137, 2018). "The subset of genes upregulated in lungs of both tumor free and metastatic Ikkβ-deficient animals comprised Tnfa, Ccl5, Ccl17, Ccl22, Cxcl1 and Csf2, although not all changes reached significance." (PMID 29682184, 2018). "Future research should also focus on increasing the sample size, incorporating animal models for in vivo validation, and further exploring the multi-cellular interactions and molecular mechanisms by which CSF2 regulates the tumor microenvironment, which may reveal new therapeutic targets." (PMID 41216204, 2025). "A modified analysis of the NUGC-3 tumor samples showed that PC14586 administration in vivo led to changes in the expression of immune and inflammatory signaling–associated genes and gene sets (TNFSF9, CSF2, IL1A, GDF15, and TNFA signaling and inflammatory response)." (PMID 39945593, 2025). "In addition, CSF2 may influence tumour growth and infiltration by regulating the differentiation and proliferation of tumour‐associated cells." (PMID 39011666, 2024). "Cxcl2, Ccl2, Ccl3, and Ccl8 can act as chemoattractants for myeloid cell recruitment in tumors, while Csf1, Csf2, and Csf3 are central to controlling the recruitment, proliferation, and differentiation of immunosuppressive myeloid cells, including macrophages and neutrophils in the tumor." (PMID 37138326, 2023). "In addition, PNT favours post-translational modification of specific chemokines and cytokines (e.g. CCL2 and CSF-2) which have been shown to favour the recruitment and infiltration of anti-tumour T cells as well as they critically alter MHC-peptide complex inhibiting T cell activation." (PMID 36161514, 2023). "Chemokines and cytokines such as CSF2, CCL12, CCL20, IL1B, and CXCL3/5/6 are significantly upregulated in the tumor microenvironment, indicating that the body is extensively recruiting and activating myeloid immune cells." (PMID 41415031, 2025). "To examine MDSC-tumor interactions, we analyzed the GSE145374 dataset, identifying CSF2, SAA2, IL6, SAA1, and BCL2A1 as the top five upregulated differentially expressed genes in SKOV3 cells after co-culture with MDSCs." (PMID 41029721, 2025). "Granulocyte-macrophage colony-stimulating factor (GM-CSF), also known as CSF2, is a key growth factor in the hematopoietic system that enhances the body’s ability to kill tumor cells by regulating the function of antigen-presenting cells." (PMID 41216204, 2025). "M1-type macrophages are generated in response to granulocyte macrophage colony stimulating factors (GM-CSF or CSF2) and stimulated by IFN-γ, lipopolysaccharide, TNF-α, which share the same properties of anti-tumor and pro-inflammation." (PMID 41333471, 2025). "M1-like macrophages are thought to be a part of the anti-tumor response by inducing an inflammatory microenvironment by factors such as TNF-α, IFN-y, IL-6, and CSF-2." (PMID 38523840, 2024). "The weight of tumors in CSF2 knockdown and IGF2BP2 knockdown groups was approximately half of those in GC-MSCs group, further substantiating the roles of CSF2 and IGF2BP2 in maintaining the tumor-promoting roles of GC-MSCs." (PMID 37865637, 2023). "AHCY-deficient SW480 cells exhibit significant upregulation of genes important for the tumor microenvironment pathway, such as MMP19, MMP24, and CSF2, as well as upregulated activation of PLAU and BCL2." (PMID 38003292, 2023). "In vivo, both CSF2 silencing and PF3758309 suppressed PAK1-driven tumor proliferation and angiogenesis." (PMID 37564209, 2023). "Significant changes have been detected in the tumor microenvironment pathway including genes MMP19, MMP24, and CSF2, as well as PLAU, BCL2, TIAM1 and Rac1." (PMID 38003292, 2023).
tumor (continued). "In line with this study, it was reported that activated inflammatory DCs induced γδT17 cells to secrete CXCL8, TNF-α and CSF2 with a concomitant accumulation of PMN-MDSC with high arginase-1 and ROS production in the tumor." (PMID 37566060, 2023). "B lymphocytes can produce immunostimulatory cytokines (e.g., IL-6, IL-4, IL12p40, IL7, INF-γ, TNF, CCL3, IL-2, and colony-stimulating factor 2 CFS2 or GM-CSF) and anti-inflammatory cytokines (IL-10, TGF-β, IL-35) even within the tumor tissue." (PMID 37046842, 2023). "To further validate these observations, we extended our analysis to cancer-derived MSCs and evaluated the impact of CSF2 and IGF2BP2 knockdown in GC-MSCs on tumor growth." (PMID 37865637, 2023). "GM-CSF, IL3, CSF2, and IL5 are important regulators of inflammation and immune suppression within the tumor microenvironment." (PMID 35574409, 2022). "M2 polarizing factors are hypoxia and acidity of the tumour microenvironment, IL4, TGFB and IL10 and CSF2." (PMID 35445563, 2022). "MDSCs, recruited by tumour secreted CSF1 and CSF2, suppress T cells including CD8+, NK cells, DCs and macrophages." (PMID 35445563, 2022). "Together with the altered CSF2, the two cell adhesion proteins, osteoblast-cadherin (CDH11) and N-cadherin (CDH2) were downregulated, suggesting that osteoclasts decrease the tumor cell ability to adhere to mesenchymal cells in the microenvironment." (PMID 35971022, 2022). "Mechanistically, KRAS drives the production of CSF2 and lactate in tumor cells by stabilizing hypoxia-inducible factor-1α (HIF-1α), a transcription factor that controls the expression of CSF2 and glycolytic genes." (PMID 33833221, 2021). "Silencing HIF-1α was found to significantly suppress the production of CSF2 and lactate in KRAS mutant tumor cells, abrogating the ability to induce TAM-like changes in macrophages." (PMID 33833221, 2021). "With increased tumor PD-L1, expression of activation and cytotoxicity marker genes, including IFNG, TNFSF9, TNFSF14, CSF2, and IL2, were downregulated in both Tnull and TCR-TMART-1, consistent with results of cytokine secretion assays." (PMID 33754038, 2021). "A variety of growth factors secreted by many tumor cells, such as CSF1, CSF2, and VEGF, are also involved in regulating the fate of the MDSC in the TME." (PMID 34858479, 2021). "Tumor-derived CSF2 increases the expression of PD-L1 in granulocytes by activating the JAK/STAT3 signaling pathway, which inhibits the anti-tumor effect of T cells and contributes to the progression of gastric cancer and hepatocellular carcinoma." (PMID 34248982, 2021). "Nevertheless, care should be taken when interpreting these findings because TGF‐β can increase CSF2 in uterine epithelial cells, WNT7A in chondrocytes, KRT17 in tumor epithelial cells, and SERPINE1 in renal epithelial cells." (PMID 34789212, 2021). "Human cancer cell lines secrete cytokines able to impair macrophage anti-tumor properties, i.e., IL-10, TGF-β, and PGE2 stimulate myelopoiesis, producing granulocyte and macrophage growth factors, i.e., M-CSF (CSF-1), GM-CSF (CSF-2), and G-CSF (CSF-3)." (PMID 34680425, 2021). "It was also reported that CSF2 increases the secretion of CXCL8 in macrophages, which further induces the expression of PD-L1 on TAMs in an autocrine manner and inhibits the anti-tumor effect of CD8+ T cells." (PMID 34248982, 2021). "After a series of validation experiments for the concerned genes, it was found that IL6, GM‐CSF (CSF2), IL11, CCL3, S100A8 and S100A9 were significantly decreased in the gut tumours of ApcMin/+ TLR4−/− mice compared with ApcMin/+ WT mice." (PMID 31650683, 2020). "CSF-2 and IL6 antibody blockade can inhibit the occurrence and metastasis of colon cancer in vivo, increase the proportion of M1 macrophages in tumor tissues, and reduce the proportion of M2 phenotypic TAMs in tumor tissues." (PMID 33224886, 2020).
tumor (continued). "In this study, the methylation status of five selected gene promoters (CDKN2A, hMLH1, MGMT, CSF2, and DIS3L2) confirmed the presence of DNA methylation in tumor tissues and matched normal tissues." (PMID 31924802, 2020). "Accordingly, our analysis of a subset of genes that had a significant Z score for similarity to proliferation of tumor cells predicted cell cycle progression through genes such as CDK4, HRAS, IL-4, CSF2, IFNG, IL-6 and STAT3." (PMID 33180876, 2020). "An array of tumor-derived chemoattractants such as CSF1, CSF2, CCL2, VEGFA, and SEMA3A contribute to the recruitment of monocytic precursors, resulting in TAMs accumulation." (PMID 31406165, 2019). "There was only one tumor suppressor (CSF2) and one cancer census gene in Cluster 3 (USP6); there are four tumor suppressors (GALR1, IRF4, PTPRT and SOX11) and one more cancer census gene in Cluster 4 (NRG1)." (PMID 28198667, 2017). "Among these differentially expressed genes, pro-inflammatory cytokines, such as IL6, CXCL1, CXCL5, CXCL8, and CSF2 were further validated as significantly downregulated in WCE-treated PC-3 and DU145 tumor tissues." (PMID 29142311, 2017). "Among the PTEN-regulated chemo- and cytokines we verified differential expression of CSF2 (also known as GM-CSF), EGF and VEGFA by tumor cells." (PMID 28008153, 2017). "CSF2, which stimulates intra-tumoral dendritic cell expansion and induces significant CD4+ and CD8+ T cell anti-tumor immune responses was the top uniquely activated UPR (most significant UPR, based on p-value of overlap) in CPA-treated GL261 tumors." (PMID 27515027, 2016). "By day 7, IFNγ, CSF2, CXCL10, GZMB, PTGS2, TNFα, CD80, CCL22, IL12a, IL13, IL1b, IL6, NOS2, and CTLA4 were significantly upregulated in the tumor-bearing mice bladders and AGTR2 and GATA3 were downregulated." (PMID 22013484, 2011). "Similarly, the downregulation of CSF2, CXCR3, and TNFSF14 in PBMCs from CRC patients suggests a potential impairment in immune activation and anti-tumor responses." (PMID 40484866, 2025). "Activation of genes related to this pathway (CSF2, SERPINE1, PDGFD, CYFIP2, IL7R, MYB, CSF1) can promote tumor cell proliferation and survival, and may also affect immune cells in the TME." (PMID 41328768, 2025). "Irradiation of radioresistant B16 tumor cells in vitro, but not MC38 tumor cells, resulted in increased levels of Csf2 transcripts and GM-CSF protein in the culture supernatant." (PMID 40146036, 2025). "The anti‐CSF2 antibody or lnc‐CSRNP3 knockout significantly reduced the CSF2 content in mouse plasma and the lnc‐CSRNP3 expression in xenograft tissues, as well as markedly decreased the tumor volume and tumor weight." (PMID 39036343, 2024). "In our work, we found that increased CSF2 after osimertinib resistance was predominantly secreted by CAFs but not tumor cells." (PMID 39036343, 2024). "Moreover, the knockdown of CSF2 and IGF2BP2 in GC-MSCs significantly slowed the rate of tumor growth relative to GC-MSCs group." (PMID 37865637, 2023). "The results of tumor growth curves showed that CSF2 overexpression MSC and P-MSC groups displayed faster tumor growth rates than control MSC groups, while CSF2 knockdown and IGF2BP2 knockdown in P-MSCs markedly reduced the tumor growth rate." (PMID 37865637, 2023). "Tumor-derived factors, such as G-CSF (also known as CSF3), GM-CSF (also known as CSF2), and IL-6 drive this myeloid bias and increase the circulating and tumor-infiltrating MDSC population, which accelerates tumor progression by suppressing T cell responses and releasing metabolic factors." (PMID 34248988, 2021). "More recently, in a gastric adenocarcinoma mouse model, it was demonstrated that gastric tumor cells produced IL-33, which resulted in mast cell activation that led to the production of macrophage-attracting factors CSF-2, CCL3, and IL-6 and subsequent tumor growth." (PMID 34063789, 2021).
tumor (continued). "Although the directing action of CSF-2 is not significant, the immunosuppressive tumor microenvironment created by CSF-2 is deeply influential to TAM reprogramming." (PMID 33505964, 2020). "Similarly, PD-L2 can be induced by the adaptive immune resistance mechanism, depending on the milieu of inflammatory cytokines in the tumor microenvironment; for example, IFN-γ, IL-4 and colony-stimulating factor 2 (CSF-2) upregulate PD-L211." (PMID 33339860, 2020). "This indicates a shift of microglia from anti- to pro-inflammatory phenotype in the absence of tumour-derived CSF2." (PMID 32390004, 2020). "Whilst CXCL6 exhibited a strictly FB-type-specific induction profile regardless of the invasiveness of the tumor cell line, CSF2 was only induced in co-cultures of invasive cell lines regardless of the partnered FB type." (PMID 25919140, 2015). "Similarly, IL33 impaired the killing ability of HDNs against tumor cells, an effect that was rescued by DGAT1/2 inhibition; CSF2 did not impair the killing ability of HDNs against tumor cells." (PMID 41214328, 2025). "Csf1, but not Csf2 or Il4, was highly expressed in tumors compared with tumor-distant liver tissues, implying that enhanced local production of M-CSF may stimulate KC mobilization and proliferation." (PMID 36821387, 2023). "NK cells lyse tumour cells via granzyme and TNFSF10 and FASLG, secrete cytokines, primarily Th‐1 type cytokines such as IFNG, TNF and granulocyte/ monocyte colony‐stimulating factor (CSF2) which facilitate the activation of T cells and other innate immune mediators." (PMID 35445563, 2022). "This implied that CSF2 maybe not the sole factor that contributes to tumor activation of macrophages, and there may exist other concomitant stimulation factors which abrogate the pro-inflammatory activities of CSF2-activated macrophages." (PMID 33833221, 2021). "We also identified six UPRs unique to CPA-treated B16F10 tumors vs. GL261(B6) tumors that promote tumor cell survival or tissue repair and may contribute to B16F10 tumor unresponsiveness: activated UPRs KDM5B, RBL2 and SPARC; and inhibited UPRs FOXM1, CD24 and CSF2)." (PMID 27515027, 2016). "However, future additional experimental validation of CSF2 and its regulation, as well as proper exclusion of IL-13 and TSLP in the effects of NCTD on CRC or other types of tumor cells may provide further insights into the particular anticancer mechanism of NCTD." (PMID 40394236, 2025). "αCD40-induced changes in tumour inflammatory mediators IL-1α, RANTES (CCL5) and GM-CSF (CSF2) at the mRNA level did not translate into significant increases in protein expression (data not shown)." (PMID 26918344, 2016). "Interestingly, the receptor for CSF2, CSF2RA, was not expressed on astrocytes in single culture but was significantly up-regulated when co-cultured with tumor cells." (PMID 28008153, 2017).
cancer (921 papers, 1997 to 2026). A tumor composed of atypical neoplastic, often pleomorphic cells that invade other tissues. "CCL2 and CSF2 were predominantly distributed in Mono-Macro cells, and cancer-associated fibroblast (CAF) showed sporadic expression." (PMID 40535567, 2025). "CSF2 is linked to the promotion of cancer stem cells via the activation of STAT3 and myeloid-derived suppressor cells." (PMID 36980301, 2023). "It has been reported that CSF2 is closely associated with the poor prognosis of some cancers and is also an important signaling molecule in the regulation of cancer cell stemness." (PMID 37786776, 2023). "Herein, we identified IGF2BP2 as a regulator of the m6A modification of CSF2, which in turn mediated the transformation of carcinoma-associated MSCs, which provides novel insights into the biological roles of m6A modification in MSC reprogramming in cancer." (PMID 37865637, 2023). "These agents are effective for some types of cancers, particularly those overexpressing GM-CSF/CSF2, but frequently cause severe adverse effects, thereby limiting dose escalation." (PMID 30597969, 2018). "In addition, the s-CSF2-Ab levels were associated with several cancers, including EC, CRC, GC, and LC." (PMID 36844744, 2023). "CSF2 is primarily secreted by activated monocytes, macrophages, fibroblasts, smooth muscle cells, endothelial cells, and various cancer cell types." (PMID 41543632, 2026). "CSF2 (granulocyte–macrophage colony-stimulating factor, GM-CSF), a member of the CSF family, is produced and secreted by various cell types, including cancer cells." (PMID 41154660, 2025). "Among these, Col4a6 and Csf2 genes participated in inflammation-to-cancer progression by regulating the PI3K-Akt and TNF pathways." (PMID 41415031, 2025). "This study revealed that CSF2 expression was significantly higher in cancer tissues than in adjacent normal tissues and was positively correlated with Stage, Pathologic_T, Pathologic_N, and Pathologic_M, as well as being associated with poorer prognosis." (PMID 41216204, 2025). "First, we validated that Csf2 expression is virtually absent in stromal cells within the NrasG12D/PtenKO TME, indicating that cancer cells are the major source of GM-CSF within the TME." (PMID 38519484, 2024). "CSF2/GM-CSF is produced both by cancer cells and CAFs when stimulated with HB-EGF, while LIF is specifically produced by CAFs." (PMID 39262776, 2024). "In epithelial ovarian cancer cells, the activation of the CSF2/p-STAT3 pathway leads to the enhancement of stem cell-like properties in cancer cells." (PMID 38003292, 2023). "Between CSF-2 and IL18R1, we chose to study CSF-2 as a potential target of PELP1 because of its proven role in cancer progression and as a secretory paracrine mediator." (PMID 34774800, 2022). "In gallbladder cancer, conventional chemotherapy supplemented with CSF2 and PD-L1 blockade was shown to decrease local cancer recurrence after surgery." (PMID 34248982, 2021). "Colony Stimulating Factor 2 (CSF2), a granulocyte macrophage-colony stimulating factor, was illustrated to have intimate associations with diverse cancers." (PMID 31894857, 2020). "The top network with the highest score yielded under IPA data was associated with cell death/survival, cancer and organismal injury/abnormality consisting of ERK1/2, Akt, and CSF2 as key nodes." (PMID 33207814, 2020). "Mesenchymal stem cells (MSCs), components of this microenvironment, have been increasingly recognized for their role in enhancing cancer progression through metabolic reprogramming induced by colony-stimulating factor 2 (CSF2) produced through Notch1 ubiquitination." (PMID 39791162, 2025). "By enhancing neutrophil polarization and promoting an immunosuppressive environment, CSF2 could potentially contribute to immune evasion and cancer progression." (PMID 41216204, 2025).